PRKRIP1 (PRKR interacting protein 1)
Description:
Required for pre-mRNA splicing as component of the spliceosome. Binds double-stranded RNA. Inhibits EIF2AK2 kinase activity (By similarity).
Synonyms: C114; FLJ13902; KRBOX3
Tractability: Small molecule: a structure with a bound ligand is known. PROTAC: its protein half-life has been measured.
Gene: Protein-coding gene on chromosome 7 (102,363,872 to 102,426,676, forward strand). Ensembl gene ENSG00000128563.
Subcellular location: Nucleus; Nucleus, nucleolus
Subcellular location (Human Protein Atlas): Actin filaments; Cytosol
Pathways (Reactome):
Metabolism of RNA: mRNA Splicing - Major Pathway
Gene Ontology:
Molecular function: protein binding; double-stranded RNA binding; protein kinase binding; protein kinase inhibitor activity
Biological process: renal system process; mRNA splicing, via spliceosome
Cellular component: actin cytoskeleton; cytosol; extracellular exosome; nucleus; post-spliceosomal complex; spliceosomal complex; U2-type catalytic step 1 spliceosome; U2-type catalytic step 2 spliceosome; nucleolus; nucleoplasm
Genetic constraint (gnomAD): Loss-of-function variants: 19 observed, 21.21 expected, observed/expected ratio (o/e) 0.9, 90% interval 0.62 to 1.32. The upper end of that interval is the gene's LOEUF score, 1.32, which puts it in group 5 of 6, group 1 being the genes least tolerant of losing a copy. Missense variants: 216 observed, 214.88 expected, observed/expected ratio (o/e) 1.01, 90% interval 0.9 to 1.12. Synonymous variants: 85 observed, 78.39 expected, observed/expected ratio (o/e) 1.08, 90% interval 0.91 to 1.3.
Homologues: Orthologues: chimpanzee PRKRIP1 (99% identical), dog PRKRIP1 (93% identical), pig PRKRIP1 (93% identical), rat Prkrip1 (93% identical), rabbit PRKRIP1 (92% identical), mouse Prkrip1 (92% identical), guinea pig PRKRIP1 (91% identical), macaque PRKRIP1 (73% identical), zebrafish prkrip1 (60% identical), tropical clawed frog prkrip1 (55% identical), Drosophila melanogaster CG8441 (35% identical), Caenorhabditis elegans F37A4.2 (34% identical).
Diseases named in the same sentence as PRKRIP1 in open-access papers:
PRKRIP1 is named in the same sentence as 1 disease in open-access papers, as found by Europe PMC text mining. Sharing a sentence is not in itself a finding about the gene and the disease.
PRKRIP1 shares sentences with these, for which no sentence is quoted: cancer (1 paper).